OR4D1 (olfactory receptor family 4 subfamily D member 1)
Description:
Odorant receptor.
Synonyms: OR4D3; TPCR16; OR17-23; OR4D4P
Tractability: Antibody: UniProt places it where antibodies can reach, with medium confidence; UniProt predicts a signal peptide or a membrane-spanning region; its Gene Ontology location is reachable by antibodies, with medium confidence.
Gene: Protein-coding gene on chromosome 17 (58,148,384 to 58,159,585, forward strand). Ensembl gene ENSG00000141194.
Subcellular location: Cell membrane
Pathways (Reactome):
Sensory Perception: Expression and translocation of olfactory receptors
Gene Ontology:
Molecular function: olfactory receptor activity; G protein-coupled receptor activity
Biological process: sensory perception of smell; detection of chemical stimulus involved in sensory perception of smell; G protein-coupled receptor signaling pathway
Cellular component: membrane; plasma membrane
Genetic constraint (gnomAD): Loss-of-function variants: 10 observed, 15.87 expected, observed/expected ratio (o/e) 0.63, 90% interval 0.39 to 1.07. The upper end of that interval is the gene's LOEUF score, 1.07, which puts it in group 4 of 6, group 1 being the genes least tolerant of losing a copy. Missense variants: 345 observed, 394.38 expected, observed/expected ratio (o/e) 0.87, 90% interval 0.8 to 0.96. Synonymous variants: 141 observed, 153.79 expected, observed/expected ratio (o/e) 0.92, 90% interval 0.8 to 1.05.
Homologues: Orthologues: chimpanzee OR4D1 (99% identical), macaque OR4D1 (96% identical), dog OR4D1 (88% identical), guinea pig OR4D1 (86% identical), mouse Or4d1 (86% identical), pig OR4D1 (85% identical), rabbit OR4D1 (85% identical). Paralogues in human: OR4D2 (78% identical), OR4D9 (63% identical), OR4D11 (62% identical), OR4D10 (62% identical), OR4D5 (60% identical), OR4D6 (60% identical), OR4Q3 (53% identical), OR4N5 (51% identical), OR4N2 (50% identical), OR4K14 (49% identical), OR4K1 (48% identical), OR4K13 (48% identical), and 116 more.
Diseases named in the same sentence as OR4D1 in open-access papers:
OR4D1 is named in the same sentence as 2 diseases in open-access papers, as found by Europe PMC text mining. Sharing a sentence is not in itself a finding about the gene and the disease. The quoted sentences say what the papers report.
Obesity (1 paper, 2023). Accumulation of substantial excess body fat. "Higher OR4D1 gene score smokers were at a greater risk of obesity (OR = 2.67 [CI = 1.35, 5.30]), while high CALML3 gene score smokers had a lower risk of obesity (OR= 0.25 [CI = 0.10, 0.62])." (PMID 37664850, 2023). "OR4D1, and OR52K1 gene scores were positively correlated with obesity, and OR2L8 and CALML3 gene scores were negatively correlated with obesity." (PMID 37664850, 2023).
infection (1 paper, 2025). The state of being infected such as from the introduction of a foreign agent such as serum, vaccine, antigenic substance or organism. "Although we used an i.c. mouse model of infection, the high expression of Or4d1 indicates the important role of the olfactory region and its connection with Cn pathogenesis." (PMID 40038673, 2025).